DUSP1 (dual specificity phosphatase 1)
Diseases named in the same sentence as DUSP1 in open-access papers (continued):
Sharing a sentence is not in itself a finding about the gene and the disease.
septic shock (1 paper, 2024). Shock caused by infection; frequently caused by gram negative bacteria, although some cases have been caused by other bacteria, viruses, fungi, and protozoa; characterized by fever, chills, tachycardia, tachypnea, and hypotension. "Results indicated that the DUSP1 gene was located in the third quadrant, distant from the origin, in the pediatric septic shock cohort." (PMID 39659576, 2024).
squamous cell carcinoma of the salivary gland (1 paper, 2024). "To investigate the potential role of DUSP1 in the context of salivary gland squamous cell carcinomas (SG-SCCs), we applied the CRISPR/Cas9 system to delete exon 2 of DUSP1 in A253 human cells, derived from a primary SG-SCC." (PMID 38951654, 2024).
tongue squamous cell carcinoma (1 paper, 2023). A squamous cell carcinoma that arises from the tongue. "Eight genes were shown to be related to the prognosis in patients with tongue squamous cell carcinoma (AXL, SCG5, VOPP1, DCBLD2, DRAM, DUSP1, AQP5, BLNK)." (PMID 37925175, 2023).
uterine infection (1 paper, 2022). "In the current study, DUSP1 was identified as a discordant, activated upstream regulator of pregnancy regulated genes in cows following uterine infection." (PMID 35358206, 2022). "A total of 14 predicted upstream regulators were identified only in healthy cows (P < 0.05), while five unique predicted upstream regulators were identified only in cows after uterine infection, including the inhibition of ISG15 and AIRE, and activation of DUSP1, NFKBIA, and PF4 (P < 0.05)." (PMID 35358206, 2022).
tumor (152 papers, 2010 to 2026). "Knockdown of CEBPB in HCT116 cells rescued DUSP1 expression and reduced pro-tumor pathways linked to hyperactive MAPK." (PMID 41411347, 2025). "Specifically, low expression of DUSP1 is linked to the development and progression of these cancers, where it is associated with poorer prognosis, higher tumor burden, and reduced survival rates in patients." (PMID 41158869, 2025). "The report further suggests that the modulation of MAPK signaling and the downregulation of DUSP1 attract tumor-infiltrating T cells and cancer-associated fibroblasts (CAFs) in OC TME." (PMID 41158869, 2025). "Lower DUSP1 levels significantly correlated with high serum alpha-fetoprotein levels and were associated with increased tumor size." (PMID 41158869, 2025). "The genes highly enriched in cluster 0, 3, and 13 CD8+ T cells from LAIT‐treated tumours were associated with T cell activation such as Fos, Jun, Pcdc1, Egr1, and Dusp1 or type I IFN responses such as Ly6a, and Ifi27l2a." (PMID 35808806, 2022). "DUSP1, as a protein phosphatase, abnormally expressed in various cancers, played a key role in tumor immunotherapy, and was associated with prognosis." (PMID 36131791, 2022). "Recently, it has been reported that DUSP1 expression promoted tumor proliferation through miR-34a, and associated with poor prognosis of OS patients." (PMID 34336699, 2021). "It has also been reported that DUSP1 was closely associated with tumor cell resistance, including GC cells." (PMID 34252149, 2021). "We found that soybean intake was significantly associated with methylated DUSP1 in tumour DNA in ER/PR-negative patients." (PMID 28220843, 2017). "Angiogenesis was associated with the tumor metastasis in the mouse model and was impaired by DUSP1, which suppressed VEGF expression." (PMID 28129656, 2017). "We analysed the associations between environmental factors and DUSP1 methylation in tumour DNA in a multivariate analysis." (PMID 28220843, 2017). "In various human cancers, abnormal expression of DUSP1 was observed which was associated with prognosis of tumor patients." (PMID 27227569, 2016). "DUSP1/MKP-1 has been implicated in acquired or intrinsic resistance to a wide range of anti tumour drugs including cisplatin, taxanes, anthracyclins and doxorubicin." (PMID 26791049, 2016). "The loss or decreased expression of DUSP1 was observed in higher histological grade tumors of the prostate, pancreas, colon, ovary, bladder, gastric, and HCC,70,74,75,77,79,80,81 which may lead to consistent activation of MAPKs and drug resistance." (PMID 41158869, 2025). "This concept is particularly strengthened by the fact that DUSP1 upregulation following traditional chemotherapies is associated with worse tumor burden and drug resistance in several malignancies and thus, DUSP1 inhibition would be expected to improve clinical outcomes." (PMID 41158869, 2025). "Through six algorithms, we identified that DUSP1 may related to tumour-infiltrating T cells and cancer associated fibroblasts (CAFs) in OVCA." (PMID 35911442, 2022). "Because of its capacity to inhibit apoptotic signals, DUSP1 has been widely studied in vivo and in vitro as a proto-oncogene and is associated with tumor progression in several types of cancer, which agrees with the changes in cell cycle and cancer-related pathways in our dataset." (PMID 34572983, 2021). "Importantly, some studies have shown an association between ERK/DUSP1 pathway activation and invasive tumor phenotypes, characterized by inducing drug resistance and poor survival." (PMID 33056982, 2020). "However, we did find significant correlations of triple-negative status with DUSP1 methylation in both tumour DNA and PBL DNA, and significant associations among soybean intake, irregular menstruation, ER/PR status, and DUSP1 methylation in tumour DNA." (PMID 28220843, 2017). "Higher DUSP1 expression in tumor nuclei staining was associated with a better survival." (PMID 27227569, 2016).
tumor (continued). "Importantly, DUSP1 modulates Tumor-Associated Macrophage (TAM) activity and signaling." (PMID 41158869, 2025). "Genes associated with MAPK signaling cascades, a major downstream pathway of EGFR signaling (AREG, JUN, DNAJB1, DUSP1), were upregulated in tumor C0 NK cells." (PMID 41082397, 2026). "Early evidence supporting a possible tumour suppressor role of DUSP1 demonstrated that its expression, together with the subsequent ERK1/2 dephosphorylation, promotes apoptosis in BC." (PMID 40943262, 2025). "At the same time, the in vivo mouse transplant tumor model further verified that CEP can significantly inhibit tumor growth by upregulating DUSP1 in tumor tissues and reducing the level of phosphorylated ERK." (PMID 41368570, 2025). "Immunostaining of normal tissue adjacent to cancer and tumor tissue found that DUSP1 highly expressed in GC." (PMID 40489463, 2025). "Depending on the context within the GBM-TME, DUSP1 can act as both a tumor suppressor and a tumor promoter." (PMID 41158869, 2025). "Combination therapy with gemcitabine and DUSP1 increased apoptotic tumor cell death, reduced angiogenesis, and improved survival in orthotopic pancreatic mouse models." (PMID 41158869, 2025). "Emerging evidence highlights its context-dependent roles in cancer progression, where DUSP1 can function either as a tumor suppressor or promoter depending on the tumor type, stage, and tumor microenvironment (TME)." (PMID 41158869, 2025). "The modulation of DUSP1 is thought to impair tumor growth and motility as well as potentiate therapeutic sensitivity in various neoplasms through the regulation of the MAPK signaling pathway." (PMID 40361912, 2025). "This reveals that all three of these genes are expressed more highly in benign tumours, although only significantly so in the case of DUSP1 (p = 2.02 × 10−12) and Fos (p = 1.18 × 10−7)." (PMID 40725480, 2025). "DUSP1 KO caused an increase in SNAIL and ERK1/2 phosphorylation and led to increased tumour growth and invasion, while DUSP1 overexpression decreased tumour growth." (PMID 40943262, 2025). "Further inhibition of PROPER expression using antagoPROPER suppresses PCa xenograft tumor growth in mice, suggesting that DUSP1 is a potential therapeutic target in PCa." (PMID 41158869, 2025). "DUSP1 (dual specificity phosphatase 1 or MAPK phosphatase 1) is a tumor-suppressor in the MAPK pathway that mediates the dephosphorylation of ERK1/2, and its downregulation seen here is likely to underpin sustained proliferative signalling." (PMID 41048341, 2025). "DUSP1 exerts context-dependent effects on tumor cell biology, likely influenced by tumor microenvironments, while mediating distinct signaling pathways across malignancies." (PMID 40535772, 2025). "In vivo, administration of the DUSP1/DUSP6 inhibitor BCI increased ERK1/2 and JNK activation, caused tumour necrosis and fibrosis, and reduced tumour volume in MPNST xenografts established with S462.TY cells or patient-derived cells." (PMID 40943262, 2025). "As an important signaling regulator, DUSP1 is involved in key processes such as tumor cell proliferation, apoptosis, and drug resistance." (PMID 40489463, 2025). "With regard to endometrioid adenocarcinoma (EEA), a type of endometrial cancer (EC), IHC analysis on tumour and normal tissue provided evidence that DUSP1 downregulation correlates with advanced stages." (PMID 40943262, 2025). "DUSP1 plays a pivotal role in modulating immune responses within the tumor microenvironment, particularly influencing CD4+ T cells, regulatory T cells (Tregs), and natural killer (NK) cells, thereby impacting CRC progression." (PMID 41158869, 2025). "Several reports indicated that the inactivation of DUSP1 activity potentiates anti-tumorigenic or pro-tumorigenic impacts on tumor cell proliferation, differentiation, and survival." (PMID 41158869, 2025).
tumor (continued). "In tumor cells, we observed activation of genes associated with cell proliferation (TMSB10, IGFBP3), migration (CCL2), signal transduction (DUSP1), and other behaviors." (PMID 38191424, 2024). "Molecularly, the anti-tumor effect of panobinostat is mediated by posttranslational obstruction of the MYC oncoprotein as a result of dual specificity phosphatase 1 upregulation, thereby leading to growth inhibition and programmed cell death." (PMID 39529166, 2024). "Overall, these data suggest that DUSP1 acts as an oncogene that drives tumor growth by blocking JNK activity." (PMID 38951654, 2024). "Despite its oncogenic role in several cancers, the overall function of DUSP1 in tumor progression remains inconclusive." (PMID 38612874, 2024). "To test the function of DUSP1 in tumor growth, we transplanted DUSP1 control and KO clones intradermally in immunodeficient mice (nu/nu)." (PMID 38951654, 2024). "For instance, depending on the cellular context, DUSP1 acts either as a tumor suppressor or an oncogene." (PMID 39095315, 2024). "Parietal peritoneal thickening showed the overexpression of LUM, MMP11, and DUSP1 in the tumor region, MMP11 and CTSK in the stromal region, and MMP11 and CTSK in the immune region (adjusted p-values ≤ 0.002)." (PMID 39135097, 2024). "There is reported that dioscin induces OS cell apoptosis by upregulating ROS-mediated P38 MAPK signaling, and Fan’s research also showed that siglec-15 promotes tumor progression in OS via DUSP1/MAPK pathway." (PMID 38218960, 2024). "DUSP1 expression was decreased in tumor tissue whereas TNF, NOX4, and LONP1 expressions were increased in tumor tissue, compared with those in normal tissue." (PMID 38758860, 2024). "Dual specificity protein phosphatase 1 (DUSP1) was used as a tumor suppressor and also affected the MAPK pathway, and it has been known to be expressed in various myeloid cells." (PMID 36769180, 2023). "Taken together, these studies suggest that DUSP1 and six antagonists are novel anti-neoplasm compounds for cancer treatment, and further understanding their biological functions will help devise more selective inhibitors with improved cellular permeability." (PMID 38139370, 2023). "Our previous study of 113 EC patients showed that DUSP1 low-expression was significantly correlated with advanced stage, higher grade tumor and myometrial invasion." (PMID 37057290, 2023). "In the present study, we aimed to investigate how DUSP1 is regulated, what other target proteins it modifies, and by what mechanism it affects tumor progression." (PMID 37057290, 2023). "Further research will be needed to investigate the connections between tumor-derived factors and DUSP1." (PMID 36387242, 2022). "Scatter plots showed the differences in DUSP1 mRNA expression levels between non-tumour tissues and OVCA tissues in every cohort." (PMID 35911442, 2022). "DUSP1 has been recognized to play a role in tumorigenesis and tumor progression, as well as the proliferation, differentiation and apoptosis of normal cells." (PMID 35741797, 2022). "Mifepristone also antagonized GR-induced SGK1 and MKP1/DUSP1 gene expression while it significantly augmented paclitaxel-induced GR-positive MDA-MB-231 xenograft tumor shrinkage in vivo." (PMID 35761157, 2022). "Among various tumor suppressors, dual specificity phosphatase 1 (DUSP1) inhibits ERK signaling and inhibits cell cycle progression in HCC cells." (PMID 35453543, 2022). "The UPF1 overexpression-mediated increase of DUSP1 activated tumor suppressor signaling, ultimately inhibiting cell growth." (PMID 35453543, 2022). "The role of DUSP1 in the tumour microenvironment (TME) of OVCA was explored via estimating immune infiltration." (PMID 35911442, 2022).
tumor (continued). "Following that, we evaluated the expression of DUSP1 in muscle and tumor tissues of 97 patients with gastrointestinal tumor by qPCR assay." (PMID 36387242, 2022). "Accumulating evidence indicates that DUSP1 is involved in tumor cell proliferation, differentiation, transformation, cycle arrest, and apoptosis by regulating the MAPK signaling pathway." (PMID 34252149, 2021). "These exosomes significantly suppressed the proliferation of BC cells by targeting DUSP1, inhibiting the growth of tumor in vivo." (PMID 32627968, 2020). "In conclusion, our findings provide robust evidence that exosomal miR‐133b functioned as a tumor inhibition factor targeting DUSP1 in BC proliferation." (PMID 32627968, 2020). "Downregulation of DUSP1 increased JNK1/2 phosphorylation to a greater extent in PKR+/+ than PKR−/− tumor cells." (PMID 31086176, 2019). "Next, we addressed DUSP1’s function in mouse NEU tumor cells by targeting its expression with two different shRNAs." (PMID 31086176, 2019). "In our study, both FOXO1 and DUSP1 presented correlation with miR-96 that is considered as a tumor inducer in researches." (PMID 31579447, 2019). "In the present study, we demonstrated that LINC01111 expression levels are clearly decreased and that the SAPK/JNK signaling pathway is significantly activated by the downregulation of DUSP1 protein in PC, which promotes tumorigenesis and tumor metastasis." (PMID 31767833, 2019). "Increased DUSP1 expression was inversely proportional to JNK1/2 phosphorylation in PKR−/− compared with PKR+/+ tumor cells." (PMID 31086176, 2019). "We further investigated the role of DUSP1 in the anti-tumor effects of combined Gefitinib and MPA treatment." (PMID 29383165, 2017). "In pancreatic ductal adenocarcinoma, DUSP1 enhances anti-tumor effects of Gemcitabine by promoting apoptosis and suppressing tumor growth and angiogenesis." (PMID 29383165, 2017). "Our data demonstrates that Gefitinib enhances anti-tumor properties of MPA via DUSP1 in EC cells, both in-vitro and in-vivo." (PMID 29383165, 2017). "In spite of the partial effect, our study indicates that DUSP1 plays an important role in the anti-tumor effects of Gefitinib and MPA treatment combination." (PMID 29383165, 2017). "Opposite effects observed in other tumors suggest the function of DUSP1 in modulating tumor bioactivity is complex and depends on the specific tumor context." (PMID 28129656, 2017). "This is the first study to report the modified effects of soybean consumption on DNA methylation in tumour by ER/PR status, and we provide preliminary evidence on potential epigenetic changes through DUSP1 methylation in triple-negative patients." (PMID 28220843, 2017). "Downregulating DUSP1 allows for proliferation and increased tumor mass in the more advanced stages of tumorigenesis by enhancing ERK/MAPK signaling pathway." (PMID 27227569, 2016). "Though DUSP1 plays a controversial role in carcinogenesis in different tumors, its role in tumor progression is relatively uniform." (PMID 27227569, 2016). "Tsujita E 29 reported that 11/77 patients were detected lower levels of DUSP1 in tumor tissues in comparison with the levels in normal tissues, but no big difference in another 66 patients." (PMID 27227569, 2016). "In this review, we will focus on the function and mechanism of DUSP1 in tumor cells and tumor treatment." (PMID 27227569, 2016). "Up-regulation of DUSP1 in the early phase of cancer helps the tumor to evade JNK1-induced apoptosis, whereas down-regulation of DUSP1 allows for proliferation and increased tumor mass in the more advanced stages of tumorigenesis." (PMID 26158762, 2015). "DUSP1 was identified to be a target of miR-101, a tumor-related miRNA that is induced after cellular activation via LPS." (PMID 26158762, 2015).